NEK2 (NIMA related kinase 2)
Diseases named in the same sentence as NEK2 in open-access papers (continued):
Sharing a sentence is not in itself a finding about the gene and the disease.
tumor (continued). "We used the CIBERSORT method to examine the tumor microenvironment (TME) of ccRCC patients with varying NEK2 gene ex-pression to further evaluate the relationship between the makeup of different immune cells and NEK2 gene levels." (PMID 38758909, 2024). "In our own validation cohort, double immuno-fluorescence also indicated greater expression of the NEK2 gene in advanced tumor stages." (PMID 38758909, 2024). "In our prior research, we demonstrated experimentally that the overexpression of NEK2 potentially led to tumor development and predicted a poor prognosis in ESCC patients." (PMID 38783335, 2024). "Our results showed that NEK2 expression was elevated in ccRCC tissues and its high expression was related to big tumor mass, higher grades, higher stages, distant spread, and shorter PFS and OS rates." (PMID 37600577, 2023). "The median IHC score was 5 (IQR: 4–8), significantly higher than those 3 (IQR: 2–4.25) in para-tumor epithelia (P < 0.001), where the NEK2 was most expressed around the base layer." (PMID 35705994, 2022). "The results showed that NEK2 overexpression significantly increased the volume of tumor when compared with control mice." (PMID 35031599, 2022). "NEK2 depletion blocks cell cycle progression and tumor cell growth, making it an ideal therapeutic target." (PMID 35139887, 2022). "The knockdown of NEK2 played an anti-tumor role in vivo and was accompanied by a lower level and nucleus shuffling of YAP1." (PMID 35705994, 2022). "The intracranial xenograft tumor model was subsequently utilized to verify the promotion of NEK2 overexpression on the tumorigenicity of GBM cells in vivo." (PMID 35031599, 2022). "The immunoreactivity score of immunohistochemistry also confirmed the elevation of NEK2 in tumor samples." (PMID 34168996, 2021). "Inhibition of NEK2 expression can significantly inhibit tumor growth in vivo and in vitro, and NEK2 was also identified as a hub gene in ESCC." (PMID 34818353, 2021). "Although previous studies indicated that NEK2 promoted tumor cell proliferation, tumor progression, and drug resistance 16, functional studies linking NEK2 with pituitary tumorigenesis are exiguous." (PMID 33754007, 2021). "The Nek2 inhibition appears to be advantageous in decreasing expression level of PD-L1 to enhance lymphocyte infiltration and promote anti-tumor immunity in PC suppression." (PMID 34943856, 2021). "So, we further assessed the proliferation of tumor by Ki67 staining, and the results showed Ki67 staining scores in the control group were significantly higher than NEK2 knockdown group." (PMID 34168996, 2021). "GH3 cells stably transfected with NEK2 shRNA or vehicle were inoculated in 6-week-old nude female mice; and relative to vehicle-treated control mice, NEK2 knockdown significantly inhibited tumor growth." (PMID 33754007, 2021). "NEK2 has been identified as a pro-oncogenic protein that facilitates the growth and glycolysis of tumor cells." (PMID 34168996, 2021). "Since PD-L1 is a well-recognized and quite important factor in the mediation of tumor immune resistance, we further investigated the regulatory effects of NEK2 on PD-L1 expression." (PMID 34315872, 2021). "In comparison with wild-type (WT) control cells, NEK2 KD-cells displayed significantly weakened resistance to T cell-mediated tumor cell-destruction in vitro." (PMID 34315872, 2021). "Recent studies have shown that circFBXW7 plays a tumor inhibitory role by reversing the expression of NEK2 and mammalian target of rapamycin (mTOR), promoting the expression of PTEN in tumors." (PMID 34112159, 2021).
tumor (continued). "In support of this, the specific NEK2 inhibitor significantly enhanced T cell-mediated tumor cell-destruction in vitro." (PMID 34315872, 2021). "In univariate Cox regression analysis, HCC recurrence, pathologic stage, tumor size, and NEK2, NDC80 and CEP250 mRNA expression were all significantly associated with HCC patients’ survival." (PMID 33109182, 2020). "Our analysis of NEK2 expression in human tumours showed that in kidney and thyroid the expression of NEK2 is higher in tumour tissues." (PMID 31906878, 2020). "By employing siRNA by a portal venous port–catheter system, the authors observed that the tumor volumes of NEK2 siRNA-treated mice were significantly lower, and the survival time was prolonged." (PMID 32294979, 2020). "The subcutaneous tumour‐bearing model of mice showed that compared with the blank group and the NC group, the si‐NEK2 group exhibited shorter tumour formation time with the slow growth rate and smaller tumours." (PMID 32558224, 2020). "USP7 is known to regulate drug resistance by stabilizing its targets, which include a range of oncogenes and tumor suppressors, NEK2 is one of the USP7 targets." (PMID 31955515, 2020). "NEK2 plays important roles in regulating the mitosis process, including chromatin separation, spindle assembly, centrosome division and tumor drug resistance." (PMID 33109182, 2020). "Together, these results show that Nek2 knockdown mitigates sorafenib resistance and improves the anti-tumor effects of this drug." (PMID 31319849, 2019). "To seek the potential sources of heterogeneity of the combined HR for OS, we performed the subgroup analysis based on tumor type, sample size, ethnicity, and detection methods of NEK2 expression and analysis type." (PMID 30578380, 2019). "We also analyzed 29 pairs of HCC tissues, comparing them to corresponding non-tumor tissues, by western blotting and showed that there was a significant increase in Nek2 protein levels." (PMID 31319849, 2019). "Whereas, overexpressed circ-FBXW7 induced the tumor suppression via reversing the expressions of NEK2, mTOR, and PTEN." (PMID 31519156, 2019). "We further analyzed the correlation between Nek2 expression and tumor pathologic stage based on the TCGA cohort and found a significant difference in Nek2 levels between the low/intermediate-grade and high -grade groups." (PMID 31319849, 2019). "To determine the correlation between NEK2 expression and cell proliferation, we performed Ki67 immunostaining on tumor engraftment." (PMID 30295336, 2019). "Gleason score, clinical tumor stage, lymph node involvement, margin status, NEK2, BUB1 and NCAPG in 9-genes cluster were significant by univariate Cox proportional hazard regression analysis." (PMID 31273254, 2019). "First of all, the roles of NEK2 overexpression in the tumor progression of HCC have been explored in a large number of recent studies." (PMID 30578380, 2019). "The percentage of HCC tissues expressing high levels of Nek2 was higher than that with non-tumor tissues." (PMID 31319849, 2019). "NEK2 was altered in 22.9% of analyzed tumor samples and found interacted with the α-tubulin isoforms TUBA1A, TUBA4A, the β-tubulin isoforms TUBB, TUBB4A, TUBB4B and all the γ-tubulin isoforms." (PMID 30126203, 2018). "The NEK2 expression levels significantly correlated with HBsAg, largest tumor size, Edmonson grading, macro- and micro-vascular invasion, Milan criteria, UCSF criteria, and Hangzhou criteria." (PMID 28881785, 2017). "Former studies from our group and others have indicated that NEK2 promotes tumor cell proliferation, tumor progression, and drug resistance." (PMID 28086949, 2017). "Tumor xenograft data from Balb/c nude mice demonstrated that HCC cells with high NEK2 expression formed larger tumors than those with low NEK2 expression." (PMID 28881785, 2017). "NEK2 has been identified as an oncogenic protein which promotes tumorigenesis, tumor progression, and drug resistance." (PMID 28086949, 2017).
tumor (continued). "Further, we confirmed that high NEK2 expression promoted cell proliferation, colony formation, migration and invasion in vitro and tumor growth in vivo." (PMID 28881785, 2017). "High NEK2 expression correlated with tumor size, pathological grade and macro- and microvascular invasion." (PMID 28881785, 2017). "In summary, our study demonstrates that NEK2 is frequently overexpressed in HCC and is associated with aggressive HCC tumor phenotype." (PMID 28881785, 2017). "Elevated Nek2 expression has also been noted in colorectal cell lines, as well as in tumor biopsies." (PMID 22040655, 2011). "Further, Nek2 siRNAs significantly reduced tumor burden in mice femorally injected with either MCF7 (ER-positive) or MDA-MB-231 (ER-negative) cells." (PMID 22040655, 2011). "Finally, using a humanized mouse model of EBV-driven lymphomagenesis, we demonstrate NEK2 inhibition significantly decreased tumor burden and tumor incidence while prolonging survival." (PMID 42133805, 2026). "Mechanistically, NEK2 drives tumor progression by modulating the Hippo pathway." (PMID 41256331, 2025). "Therefore, the tumor-promoting effect of NEK2 was mainly attributed to its crucial role in promoting the cell cycle." (PMID 40220284, 2025). "Circ-FBXW7 acts as a tumor-suppressive RNA by regulating NEK2, mTOR, and PTEN pathways." (PMID 41373479, 2025). "Moreover, it is feasible that cotargeting of CDK4/6 and NEK2 will effectively induce intolerable mitotic defects in tumor cells, while sparing normal cells." (PMID 39826695, 2025). "Notably, targeting NEK2 has been shown to inhibit cervical tumorigenesis and enhance tumor sensitivity to radiotherapy, highlighting its potential as a therapeutic target." (PMID 41256331, 2025). "Furthermore, in vivo experiments demonstrated that NEK2 overexpression enhanced the tumor growth, angiogenesis and lung metastasis of DLD-1 cells, whereas the overexpression of RhoGDI1 aa 112–134 restored the enhancement promoted by NEK2." (PMID 39768163, 2024). "Thus, NEK2 is expected to be a potential therapeutic target in ESCC patients exhibiting high NEK2 expression in tumor cells." (PMID 38783335, 2024). "We found that patients with advanced tumor stages had higher levels of the NEK2 gene." (PMID 38758909, 2024). "This suggests that ccRCC tumors overexpressing the NEK2 gene may be a hot tumor for 1 day because our findings indicated a strong link between NEK2 expression and the majority of markers of activated T cells in ccRCC, specifically CD8+/CD4 + T cells." (PMID 38758909, 2024). "Moreover, upon LPS stimulation, NEK2 overexpression plays a crucial role in tumor metastasis and invasion by initiating and promoting epithelial-mesenchymal transition (EMT)." (PMID 39610830, 2024). "However, this NEK2-mediated tumor growth enhancement was effectively reversed by the expression of the RhoGDI1 aa 112–134 fragment." (PMID 39768163, 2024). "It showed NEK2 expression was positively correlated with tumor stage." (PMID 38758909, 2024). "The NEK2 gene significantly correlated positively with the stage of the tumor." (PMID 38758909, 2024). "Among them, NEK2 presented the highest differential expression in LUAD tumor tissue." (PMID 38721812, 2024). "Furthermore, NEK2 inhibition significantly prolonged survival and reduced tumor burden in a PEL mouse model." (PMID 38592451, 2024). "NEK2, a downstream target of miR‐486‐5p, presented highest differential expression in tumor tissue." (PMID 38721812, 2024). "Moreover, in vivo studies showed reduced tumor growth and lung metastasis when the NEK2–RhoGDI1 interaction was disrupted." (PMID 39768163, 2024). "It demonstrated that NEK2 is crucial to the emergence and metastasis of most tumor." (PMID 38758909, 2024).
tumor (continued). "The elevated expression of NEK2 was positively related ro the tumor size (P=0.015), higher grades (P=0.002), higher stages (P=0.013), distant spread (P=0.004), tumor recurrence, shorter progression-free survival (PFS) rate, and overall survival (OS) rate (P<0.001)." (PMID 37600577, 2023). "Since we identified splicing factors that are co-expressed and interact with NEK2 in this tumor subtype, we asked if a common transcription factor could promote their expression." (PMID 35530315, 2022). "Moreover, we conducted wound healing assays and matrigel invasion assays to explore the effect of NEK2 knockdown on tumor malignancy in GBM cells." (PMID 35031599, 2022). "Furthermore, the intracranial xenograft tumor model identified the promotion of NEK2 on the tumorigenicity of GBM cells in vivo." (PMID 35031599, 2022). "In addition, Kaplan-Meier analysis showed that NEK2 knockdown increased the survival rate of xenograft mice, indicating that NEK2 knockdown inhibited tumor proliferation in vivo." (PMID 35031599, 2022). "Moreover, NEK2 is correlated to various aspects of malignant transformation, including tumorigenesis, tumor progression and therapeutic resistance." (PMID 35031599, 2022). "The expression of NEK2 in tumor tissues was higher than that in healthy tissues." (PMID 35368696, 2022). "The result shows that decreased NEK2 levels inhibit tumor growth of DLBCL cells in vivo." (PMID 34168996, 2021). "Another study found that in mice with subcutaneous transplantation of pancreatic cancer cells, after injection of NEK2 siRNA around the tumor, tumor growth was significantly inhibited, the survival time of mice with peritoneal metastasis was prolonged, and the survival rate was increased." (PMID 34706700, 2021). "Moreover, Tumor Immune Estimation Resource (TIMER) results showed that the transcriptional levels of NEK2 were positively correlated with immune infiltration of B cells and CD4+ T Cell." (PMID 34834441, 2021). "Interestingly, the expression of both NEK2 and PD-L1 was also observed in macrophages, DCs, and MDSCs in addition to tumor cells." (PMID 34315872, 2021). "Lastly, we further constructed a xenograft tumor model to confirm the function of NEK2 in vivo." (PMID 34168996, 2021). "NEK2 was showed to promote tumor growth, angiogenesis, and metastasis in vivo." (PMID 33946043, 2021). "Furthermore, tumor-bearing C57BL/6 and nude mice were individually administrated with NEK2 inhibitor and tumor growth was significantly suppressed in C57BL/6 mice but not in nude mice." (PMID 34315872, 2021). "The xenograft tumor model checks the influence of NEK2 on tumor growth in vivo." (PMID 34168996, 2021). "Prospective studies in vivo will determine whether genetic and pharmacological inhibition of Nek2 prevents p53LOH and alleviates tumor progression." (PMID 33267874, 2020). "Thus, our study provides a potential novel treatment strategy in aggressive MM patients who express high NEK2 in tumor cells." (PMID 31955515, 2020). "In addition, NEK2 gene has been reported to promote tumour development through the Wnt signalling pathway." (PMID 32558224, 2020). "Finally, NEK2 overexpression contributed to HCC tumor growth, migration, and angiogenesis by pAKT/NF-κB (factor nuclear kappa B)." (PMID 32294979, 2020). "Moreover, high levels of NEK2 were correlated with the tumor nodule number and recurrence, and with the expression of phospho-AKT (V-akt murine thymoma viral oncogene homolog) and MMP-2 (72 kDa type IV collagenase also known as matrix metalloproteinase-2)." (PMID 32294979, 2020). "Nek2 expression level of low/intermediate and high differentiated tumor grade using TCGA cohort." (PMID 31319849, 2019).
tumor (continued). "Further, a xenograft tumor model showed that Nek2 knockdown could improve the anti-tumor effect of sorafenib, whereas an analysis of tumor proteins showed that Nek2 regulates β-catenin protein levels and its nuclear translocation in vivo." (PMID 31319849, 2019). "Overexpression of NEK2 promoted tumor growth in vivo (P = 0.03)." (PMID 30295336, 2019). "Consistently, a xenograft tumor model showed that the combination of Nek2 knockdown and sorafenib treatment could significantly inhibit tumor growth compared to that in the control, single knockdown, or sorafenib treatment only groups." (PMID 31319849, 2019). "In addition to those signaling pathways above, several studies demonstrated that Wnt/β-catenin pathway plays a critical role in the NEK2 overexpression-meditated tumor progression." (PMID 30578380, 2019). "An analysis of tumor weights at the end of the experiment also indicated that Nek2 knockdown could significantly improve the efficacy of sorafenib treatment." (PMID 31319849, 2019). "Furthermore, the expression of YWHAQ and NEK2 was significantly higher in luminal B compared to luminal A tumours in TCGA ER+/HER2− tumours." (PMID 31892336, 2019). "Collectively, these data suggested that NEK2 promoted HCC tumor growth in vivo." (PMID 28881785, 2017). "However, the effects of Nek2 overexpression in affecting tumor growth rates of shE2F3 and shE2F3; GFP cells were inconclusive." (PMID 26512919, 2015). "Small molecules, such as INH (inhibitor for Nek2 and HEC1 binding which disrupt HEC1/Nek2 interaction), may ablate tumor progression by triggering Nek2 degradation through a death-trap mechanism." (PMID 25485281, 2014). "The immunohistochemistry staining for NEK2 was mostly positive in the cytoplasm of the tumor cells." (PMID 25202351, 2014). "In conclusion, the data indicate that compared with Mcm7 and Ki67, NEK2 may be a more effective tumor proliferation marker of poor prognosis for NSCLC patients, and that NEK2 may represent a novel potential target for NSCLC therapeutic intervention." (PMID 25202351, 2014). "Moreover, the expression of NEK2 in different tumor grades was also significantly different." (PMID 38758909, 2024). "Therefore, to test whether the interaction between NEK2 and RhoGDI1 is related to in vivo tumor growth and metastasis, we used NEK2-overexpressing cell lines." (PMID 39768163, 2024). "Therefore, the expression of NEK2 may be helpful in determining tumor progression and disease prognosis." (PMID 34712733, 2021). "Interestingly, NEK2 was also expressed in multiple immunosuppressive populations, such as myeloid-derived suppressor cells (MDSCs), dendritic cells (DCs), and macrophages, although the expression-positive rate was lower than that in tumor cells." (PMID 34315872, 2021). "We observed that either single knockdown of Nek2 or sorafenib treatment could inhibit tumor growth; however, the combination of Nek2 knockdown and sorafenib treatment resulted in the most significant inhibition of tumor growth." (PMID 31319849, 2019). "Moreover, compounds (INHs and TAIs) that specifically disrupted the Hec1/NEK2 interaction via direct Hec1 binding and caused NEK2 degradation significantly suppressed tumor growth in vivo without obvious toxicity." (PMID 27764815, 2016).